IL15 (interleukin 15)
Diseases named in the same sentence as IL15 in open-access papers (continued):
Sharing a sentence is not in itself a finding about the gene and the disease.
tumor (continued). "Administration of IL-15:IL-15Ra complexes results in the emergence of a distinct CD49a+ CD11b+ NK cell compartment, not normally present within tumors, that retains a highly cytotoxic profile and contribute to improved tumor control." (PMID 38267402, 2024). "Also, Ccl2, Ccl7, and IL-15 which have anti-tumor responses were upregulated in this cluster, which likely contributes to the IFNα-mediated antiphagocytic activity of macrophages." (PMID 39559365, 2024). "Research conducted by Milos has demonstrated that IL-15 may promote tumor immunity by inducing circulating CD8 T-cells and NK-cells." (PMID 38690276, 2024). "Next, we investigated the impact that the IFN-α/β/IFN-γ/IL-15 pathways have on tumor shrinkage." (PMID 38758367, 2024). "Indeed, myeloid cells associated with a favourable clinical response expressed transcripts associated with tumour-residing CCR7+ DCs, including CCR7, CD274, IL15, PVR and CD70." (PMID 38267413, 2024). "Furthermore, ectopic expression of ID3 in hiPSC-Macs also increased their production of the chemokines CCL3, CCL4 and CCL5, and the cytokines IL-12, IL-15 and IL-18 in response to tumour cells in vitro." (PMID 38326607, 2024). "However, prolonged IL-15 stimulation results in NK cell exhaustion, characterized by decreased tumor control and diminished mitochondrial metabolic function." (PMID 39087476, 2024). "An increased amount of IL-15 in the tumor interstitial fluid could be released predominantly from dead tumor cells, as we observed necrosis of LLC cells in the subcutaneous tumors." (PMID 38637902, 2024). "Importantly, a second infusion of CAR+IL-15-NK cells showed increased efficacy and allowed for more effective control of tumours demonstrating that the treatment schedule of CAR-NK cells will need to be carefully assessed to optimize patient outcomes." (PMID 38223411, 2024). "Therefore, it was shown that IL-21 in combination with IL-15 enhanced the antitumor effect of CD8+ T lymphocytes leading to tumor regression in established melanoma." (PMID 38638431, 2024). "Notably, past reports have shown that stimulating NK cells with IL-12, IL-15, and IL-18 endows them with memory-like properties, better anti-tumor activity, and persistence." (PMID 38711506, 2024). "After binding to IL-15Rα, IL-15 is trans-presented to the IL-2R/IL-15Rβ and -γ heterodimer expressed on effector T, B, and NK cells, thereby enhancing survival and maturation of the effector cells for killing tumor cells." (PMID 38368374, 2024). "Additionally, understanding the effect of IL-15 secretion by tumor-specific NK cells in the tumor microenvironment is crucial." (PMID 38690288, 2024). "Additionally, IL-21 in combination with IL-2 and IL-15 was used to obtain the central memory tumor infiltrating T-cells from patients with glioblastoma and pancreatic tumors." (PMID 38638431, 2024). "With increased IL-15 levels in OC ascites tumor microenvironment, we speculate that the cytokine milieu may be a driving factor of the differentiation from conventional NK cells to tissue-resident cells." (PMID 37444472, 2023). "It will be interesting to examine whether the macrophage-IL15-NK cell axis elicited by zymosan treatment induces enhanced cytotoxicity against tumor cells in vitro and in vivo." (PMID 37570749, 2023). "Regarding molecular markers, IL-15 is known to act as an immune-enhancing cytokine that is crucial for the survival, proliferation and functions of NK, T and B cells, which exhibited in vitro anti-tumor activity in TNBCs." (PMID 37511057, 2023). "Therefore, CAR T cells engineered to co-express IL-15 produced better tumor control in a mouse model." (PMID 37409128, 2023). "Furthermore, the 4T1 tumor model was also established to compare the therapeutic outcomes of heterodimeric IL-15 (IL-15:IL-15Rα) and the MIST platform." (PMID 37875481, 2023).
tumor (continued). "Similarly, IL-15 and IL-21 were designed to be fused with the anti-PD-1 antibody to yield fusion proteins αPD-1-IL-15R and PD-1Ab21, respectively, for tumor rejection." (PMID 38049832, 2023). "Thus, this TriKE is a unique NK engager with cytokine signaling, tumor-specific targeting, and a single intramolecular ADCC, which drives specific tumor-killing and induces NK cell proliferation and survival via IL15 fragments." (PMID 37190251, 2023). "In the present study, it was found that although exercise could not improve the expression of IL-15 in the plasma of normal mice, the content of IL-15 in the plasma of tumor-bearing mice after 12 weeks of treadmill exercise was significantly increased." (PMID 37585912, 2023). "On the contrary, very recent evidence indicates that triggering receptor expressed on myeloid cells 2 (TREM2) confers a pro-tumorigenic program to macrophages that interferes with IL-15 release by tumor-infiltrating DCs, thus negatively affecting NK cell activity." (PMID 37298470, 2023). "Collectively, these findings indicated that biNV-IL-15 could produce CD3+CD8+ CTLs in an antigen-specific manner in vivo via the spatiotemporally synchronous provision of IL-15 and tumor antigen to CD8+ T cells." (PMID 37875481, 2023). "Similarly, the functional relevance and mechanisms of XIST in inhibiting tumor suppressive cytokine/chemokines (i.e., IL-7, IL-15, and IL-18) need to be determined." (PMID 36922677, 2023). "The binding of KD033 to PD-L1+ tumor cells seemed to focus the IL-15 responses as KD033 could act as the costimulatory signal and checkpoint blocker for CD8+ T cells when KD033is bound to PD-L1+ tumor cells." (PMID 36454338, 2023). "In addition, when combined with a PD-1 blockade, IL15-armed vvDD vaccinia virus led to dramatic tumor regression." (PMID 38002466, 2023). "Similarly, it has been shown that NK cells, CD8+ T cells and γδ T cells exhibit cytolytic potential upon IL-15 stimulation in various tumor models." (PMID 37923822, 2023). "It is also important to delineate the mechanisms of IL15 production in tumor cells and the upstream regulatory factors of IL15 might be potential pharmaceutical target." (PMID 36959575, 2023). "The improved CD8+ T cell infiltration and reduced Tregs in dLNs indicated that biNV-IL-15 could enter LNs and effectively activate T cells through spatiotemporal integration of multivalent IL-15 self-transpresentation and tumor antigen presentation." (PMID 37875481, 2023). "Similar with the results in the tumour, IL-15 could also effectively activate the NK cells in the LNs." (PMID 37076492, 2023). "After 22 days of treatment (survival endpoint for mice with HBSS treated PC3 tumors), cyto-IL-15 combined with ADU led to complete tumor regression (98% volume reduction), significantly increased survival (undefined, p <0.01) compared to the HBSS treated cohort and cured 3 out of 5 mice (60%)." (PMID 37465665, 2023). "Notably, the percentage and absolute number of CAR MLNK cells were significantly higher than that of conventional CAR NK cells following cocultured with CD19+ tumor cells in the presence of IL-15." (PMID 37207215, 2023). "However, the inclusion of IL-7 and/or IL-21 in addition to IL15 reduced the beneficial effects of IL-15 on the phenotype and anti-tumor potency of CAR-T." (PMID 37153607, 2023). "Interestingly, these cells can be generated ex vivo and utilized in vivo to enhance the anti-tumor activity via inducible activation of IL-15 signaling." (PMID 37892995, 2023). "Next, we asked whether IL-15 could also influence the proliferation of exhausted CD8 T cells in a human tumor microenvironment." (PMID 37409128, 2023). "IL-15/IL-15Rα reverted the tumor growth effect and mediated T-cell driven tumor spheroid killing." (PMID 37923822, 2023). "Building on these data, we explored whether gene-based delivery of IL-15 to tumor cells can evoke anti-tumor immune responses and can potentiate the immune stimulatory effects of K2-Fc." (PMID 37923822, 2023).
tumor (continued). "In simpler terms, IL-15/IL-15RA could prove particularly valuable in the context of tumor cells exhibiting minimal levels of the target antigen expression." (PMID 37818365, 2023). "Furthermore, a population of IL-15-induced human circulating NKp30+FcεR1γ+ CD8+ T cells was described to exhibit high NK-like anti-tumor activity in vitro and in a preclinical xenograft mouse model in vivo." (PMID 36911660, 2023). "In one study, IL-15 administration on male Wistar rats with intraperitoneal inoculation of 108 AH-130 Yoshida ascites hepatoma cells led to a decrease in protein degradation rates compared to non-tumor-bearing mice." (PMID 37755304, 2023). "Specifically, combining ICIs with an adenovirus-based tumor antigen vaccine, an IL-15 superagonist (N-803), an anti-OX40/4-1BB, and docetaxel has demonstrated therapeutic benefits in both hot and cold tumor models, synergistically triggering an immune response." (PMID 37907738, 2023). "IL-15 administration combined with immune checkpoint inhibitors targeting PD-1/programmed cell death ligand-1 has been shown to improve tumor control and survival compared with either treatment alone in multiple murine tumor models." (PMID 37409128, 2023). "Similarly, multiple doses of CD34+ hematopoietic progenitor cell (HPC)-derived NK cells and IL-15 were given to animals bearing OvCa tumors treated with gemcitabine to improve tumor response." (PMID 37949944, 2023). "Many more examples of the combined use of IL-15 and other cytokines in tumor treatment exist." (PMID 36936961, 2023). "Furthermore, some studies suggest that the addition of Interleukin 15 (IL-15) also leads to an improved proliferation rate and anti-tumor cytotoxicity of γδ T cells." (PMID 37539052, 2023). "Furthermore, IL-2 activated NK cells that undergo apoptosis upon initial interaction with endothelial and tumor cells, while IL-15 maintains NK cell survival under the same condition." (PMID 38106519, 2023). "Nevertheless, the specific mechanisms and anti-tumor effects of NK-exos stimulated with IL-15 and other cytokines such as IL-21 (NK-exosIL−15/21) in solid tumors, including HCC, remain unclear." (PMID 37484408, 2023). "In contrast to most in vitro studies involving PBLs, we did not address the anti-tumor functions of NK and T cells individually but evaluated the interplay between CD4+ T cells, CD8+ T cells and NK cells on immune cell activation and tumor lysis upon delivery of IL-15/IL-15Rα and K2-Fc." (PMID 37923822, 2023). "In addition, interleukin-15 (IL-15) is also a vital cytokine indispensable and has vast potential as tumor immunotherapy." (PMID 36815890, 2023). "The defined biomimetic nanovaccine features multivalent IL-15 self-transpresentation, directional presentation of tumor antigen epitopes via major histocompatibility complex (MHC) molecule, and co-stimulatory molecules anchoring through a programmable procedure." (PMID 37875481, 2023). "However, only conditions containing T-cell activating beads, IL-2 or IL-15 showed statistically significant 624-MEL-GFP tumor spheroid killing." (PMID 37923822, 2023). "In addition, IL-15 has been found to enhance the antibody-dependent cell-mediated cytotoxic effects on NK cells and the efficacy of conjugated therapeutic anti-tumor monoclonal antibodies." (PMID 37251333, 2023). "Interestingly, the inhibitory effect of ICB therapy boosted by PES1 knockdown dramatically antagonized by knockdown of IL15, which suppressed the tumor-infiltrated CD8+ T cells in ESCC." (PMID 36959575, 2023). "Furthermore, the tumor resection model was also established to compare the anti-recurrence effects of heterodimeric IL-15 and the MIST platform." (PMID 37875481, 2023).
tumor (continued). "They revealed that mRNA translation in NK cells is initiated by IL-15-mediated mTOR activation; this finding increases our understanding of the mechanism of tumor-reactive NK cell activation and serves as a theoretical basis for the clinical implementation of IL-15 in adoptive NK cell therapy." (PMID 37808922, 2023). "IL-2, IL-15, and IL-21 in the IL-2 cytokine family play a positive role in anti-tumor effects, and IL-4, IL-7 and IL-9 possess pleiotropic functions, with diverse roles in cancer immunity as they can have pro-tumorigenic functions as well as anti-tumorigenic characteristics." (PMID 36936961, 2023). "Overall, providing IL-15 signaling may be necessary to maintain NK cell persistence, metabolic fitness, and enhanced anti-tumor functions in the TME." (PMID 38022679, 2023). "Moreover, previous studies have reported that IL15 superagonist-stimulated NK cells enhance in vivo antitumor efficacy by promoting tumor infiltration, and IL15-expanded KLRG1+ NK cells protect mice from pulmonary metastatic colorectal carcinoma." (PMID 37570749, 2023). "In agreement with our findings, a study in preclinical mouse models has shown that induction of type I IFNs through STING activation, results in tumor rejection by enhancing NK cell activation and cytotoxicity either directly or by upregulating IL-15 and IL-15Rα receptors." (PMID 37465665, 2023). "Indeed, the loss of IL-15 reduces the cytotoxic ILC pool and accelerates tumor growth, although the various source of IL-15 is currently under investigation." (PMID 38567059, 2023). "Cyto-IL-15 significantly increased survival to 31 days and caused a small reduction in tumor volume (not statistically significant)." (PMID 37465665, 2023). "Our results showed that IL-12, IL-15, and IL-18-activated NK cells had memory-like properties, which resulted in an increased production of IFN-γ and TNF-α upon restimulation with tumor cells and heightened cytotoxicity when compared to IL-15-maintained NK cells." (PMID 36932395, 2023). "However, when it comes to the tumor groups, not only IL-15 and Nkg2d but also NK cells were significantly higher in the TH group than in the CH group." (PMID 37585912, 2023). "Similarly, CAR-NK cells expressing IL-15 have demonstrated long-term persistence and potent anti-tumor activity in clinical trials." (PMID 37596653, 2023). "Compared with biNV, IL-15+biNV further relieved lung metastasis and tumor progression." (PMID 37875481, 2023). "Moreover, introduction of IL15 in TriKEs has been shown to improve in-vivo NK cell expansion and tumor control in mice models, taking care of the limitation of low NK cell numbers in the patient." (PMID 37228595, 2023). "CAR-T cells amplified ex vivo with IL-15 were characterized by a less differentiated phenotype, decreased expression of exhaustion and pro-apoptotic molecules, improved mitochondrial metabolism, and infusion demonstrated a greater anti-tumor response in vivo." (PMID 37251333, 2023). "However, IL-15 can shift energy metabolism from glycolysis to OxPhos by inhibiting mTOR, maintaining stemness and inducing stronger anti-tumor activity and proliferation." (PMID 37596653, 2023). "In comparison with IL-15+biNV, biNV-IL-15 suppressed the development of cancer metastasis much more effectively, achieving synergistic therapeutic outcomes of spatiotemporally synchronous provision of IL-15 and tumor antigen to CD8+ T cells." (PMID 37875481, 2023). "Furthermore, preclinical and clinical studies have demonstrated that N803 induces tumor control while overcoming the short half-life of recombinant IL-15." (PMID 37371081, 2023). "Additionally, related study has also demonstrated that IL-15 enhanced the anti-tumor activity of γδ T cells, and effectively suppressed tumor growth, and prolonged the survival of renal cancer-bearing PDX mice." (PMID 37081982, 2023). "Furthermore, IL-15 is capable of counteracting the inhibitory effect mediated by the tumor microenvironment." (PMID 38071322, 2023).
tumor (continued). "SON-1210 demonstrated robust binding affinity to albumin and exhibited the anticipated in vitro activity and tumor model efficacy that might be expected based on decades of research on native IL-12 and IL-15." (PMID 38250068, 2023). "Thus, combination of cyto-IL-15 augments the curative abscopal immunity of ADU-S100 against TRAMP-C2 tumors with a complete bilateral tumor rejection in 50% of mice." (PMID 37465665, 2023). "Notably, IL-15-treated NKEVs (IL-15-treated NK-EVs) demonstrated a more potent tumor-targeting effect and an extended circulation period." (PMID 38239346, 2023). "Especially, IL15 has been shown to promote tumor progression of CTCL." (PMID 36761972, 2023). "IL-15 can also enhance the anti-tumor activity of immune cells." (PMID 37251333, 2023). "In NK and T cells, IL-15, more than other cytokines, leads to enhanced anti-tumor immunity." (PMID 37334356, 2023). "The 3D tumor models were co-cultured with the stimulated CD8+ T cells in the presence of IL-15." (PMID 36860873, 2023). "In another research, engineered microglia as the source of IL-15 was recruited to the tumor site." (PMID 37598273, 2023). "We demonstrate the approach with a previously designed mimetic of cytokines interleukin-2 and interleukin-15—Neoleukin-2/15 (Neo-2/15)—both for trans-activating immune cells surrounding targeted tumor cells and for cis-activating directly targeted immune cells." (PMID 36316485, 2023). "To investigate whether these unique properties of iNSCs can enhance anti‐tumor properties of CAR‐T cells, we first constructed a lentiviral vector (LV) encoding human RANTES and IL‐15." (PMID 38023712, 2023). "In addition, enhanced expression of cytokines such as IL15 or IL12 will allow more recruitment of immune cells in the tumor bed." (PMID 37377603, 2023). "In addition, tumor-infiltrating Tpex cells from human RCC expanded in response to IL-15 better than the Ttex subset of CD8 TILs." (PMID 37409128, 2023). "Next we evaluated whether the transgenic IL-15/IL-15Rα expression was sufficient to induce tumor cell killing." (PMID 37923822, 2023). "These strategies include use of small molecules or genetic modification to ensure auto/paracrine cytokine (IL-15) support in vivo, enhance NK cell infiltration and function in the tumor micro-environment, block inhibitory receptors, augment antigen recognition, and enhance activating signals." (PMID 38193082, 2023). "In vivo experiments observed that these cells (CAR-T/IL-15/IlL-21) showed a larger expansion and persistence, resulting in greater control of tumor burden and survival of animals when compared to only CAR-T cells and CAR-T cells with the secretion of isolated cytokines." (PMID 36172343, 2022). "Curiously, tumor-residing BATF3+ dendritic cells have been shown to be required for T cell trafficking that can ultimately participate in the recruitment of TVM cells to tumors due to high avidity of TVM cells for IL-15." (PMID 36330506, 2022). "IL-15 is another potent immunostimulatory cytokine against tumor cells." (PMID 36419058, 2022). "Moreover, western blotting revealed that PD-L1 expression in tumor was downregulated by Ad5-Ki67/IL-15." (PMID 35765095, 2022). "We performed cancer immunotherapy using three different cytokine genes: interleukin 12 (IL12) and newly designed secreted isoforms of tumour necrosis factor‐α (TNFα) and interleukin 15 (IL15), as they have been shown to produce potent, cell‐mediated anti‐tumour effects." (PMID 35758207, 2022). "Additionally, overexpression of soluble IL-15 (sIL15) or membrane-bound IL-15 (mbIL15; IL-15Rα/IL15 complex) to generate IL-15-armored immune cells has demonstrated enhanced anti-tumor effects and cell persistence." (PMID 35806311, 2022).